VCL (vinculin)
Diseases named in the same sentence as VCL in open-access papers (continued):
Sharing a sentence is not in itself a finding about the gene and the disease.
pancreatic cancer (9 papers, 2011 to 2024). "Decreased expression of LINC01060 has been reported to be associated with the progression of pancreatic cancer by vinculin-mediated focal adhesion turnover." (PMID 38357948, 2024). "An increase in vinculin expression leads to poor prognosis in pancreatic cancer patients and is considered an unfavorable prognostic indicator." (PMID 37371811, 2023). "High expression of vinculin has been found in cancerous cells and was used as a biomarker in pancreatic cancer." (PMID 33802790, 2021). "A decrease in vinculin by AT and WZ could lead to better outcomes in the survival of pancreatic cancer patients." (PMID 37371811, 2023). "There is evidence that knockdown of Linc01060 could promote the progression of pancreatic cancer via the vinculin-mediated focal adhesion pathway turnover." (PMID 33614260, 2021). "Confirmed genes included genes already reported in the literature and proposed as biomarkers of pancreatic cancer such as S100A6, TIMP1, NF-κB, VCL and S100P." (PMID 22078386, 2011).
ovarian carcinoma (8 papers, 2011 to 2022). A malignant neoplasm originating from the surface ovarian epithelium. "As in ovarian cancer, the loss of vinculin expression in ovarian cancer cells predicts a poor prognosis for this cancer type." (PMID 36291838, 2022). "The vinculin expression was similar to what was observed in Serous and Mucinous types of Ovarian cancer cells." (PMID 27534915, 2016). "It remains to be further demonstrated whether Src and/or vinculin mediate PI3K/Akt activation by integrin β4 in the mesothelial adhesion of ovarian cancer cells." (PMID 26223322, 2015). "We found that mesenchymal-like chemoresistant IGROV1 ovarian cancer cells have higher migration properties because of their rapid regulation of focal adhesion dynamics through FAK, paxillin, vinculin, and talin." (PMID 32079527, 2020). "Ovarian carcinoma cell line OVCAR4 was unusual in having high expression of both CDH1 and VCL (arrow)." (PMID 22570691, 2012).
atherosclerosis (7 papers, 2011 to 2025). A disease characterized by the build-up of fatty material and calcium deposition in the arterial wall resulting in partial or complete occlusion of the arterial lumen. "A phosphoproteomic study identified a new VCL phosphorylation site, serine 721 (pS721), associated with a porcine atherosclerosis model." (PMID 41231303, 2025). "Additionally, VCL was significantly negatively associated with lipid and atherosclerosis score (R=-0.81, P = 0.015) and angiogenesis (R=-0.86, P = 0.007)." (PMID 38287421, 2024). "A further study is still needed to clarify the precise mechanism and role of vinculin in the progression of atherosclerosis." (PMID 36135831, 2022). "Changes in the relative content of vinculin and α-actin have been reported in the human aortic intima of patients with atherosclerosis." (PMID 21711540, 2011). "Existing research has demonstrated that vinculin represents a promising therapeutic target for conditions such as age-related heart failure, impaired angiogenesis due to dysfunctional high-density lipoprotein (dHDL), atherosclerosis, and other diseases." (PMID 39953202, 2025). "There are a variety of molecules associated with focal adhesion, such as focal adhesion kinase (FAK), integrin, talin, and vinculin, and their activities are related to the development of hypertension, atherosclerosis, and thrombosis, contributing to the progression of AIS." (PMID 35360855, 2022). "Vinculin concentrations are unlikely to reflect atherosclerosis and inflammation in coronary arteries." (PMID 36135831, 2022).
hypertrophic cardiomyopathy (7 papers, 2012 to 2025). "Vinculin protein encoded by VCL is a cytoskeleton protein related to extracellular matrix adhesion and connection, and its mutation may lead to dilated and hypertrophic cardiomyopathy." (PMID 36303204, 2022). "As vinculin expression is upregulated in hypertrophic cardiomyopathy, and when plated on stiff substrates, the interaction between vinculin and integrin acts as a novel therapeutic strategy." (PMID 40869375, 2025). "Specifically, plating wildtype cardiac myocytes on stiff hydrogels increased integrin and vinculin expression and recapitulated the hypermetabolic state evident in hypertrophic cardiomyopathy." (PMID 40869375, 2025). "Finally mutations in VCL have been linked to hypertrophic cardiomyopathy, a condition not observed in P1 and P2." (PMID 22238637, 2012).
cervical carcinoma (6 papers, 2009 to 2025). A carcinoma arising from either the exocervical squamous epithelium or the endocervical glandular epithelium. "VCL were also detected in patients with cervical cancer, and VCL expression was associated with TNM stage, this was in line with previous study." (PMID 33833775, 2021). "Our results primarily revealed that the expression of VCL was reduced in cervical cancer tissues and was associated with tumor metastasis." (PMID 34923985, 2021). "In cervical cancer, the exosomal transfer of hsa-miR-663b into endothelial cells was shown to suppress vinculin, thereby facilitating angiogenesis." (PMID 40724871, 2025). "IHC analysis of 88 patients was performed to explore the distribution of VCL in cervical cancer, and the results showed that VCL was downregulated in cancer tissue compared with normal cervix." (PMID 34923985, 2021). "WB and PCR results showed that the protein and mRNA levels of VCL in cervical cancer tissue were significantly lower than those in normal cervix." (PMID 34923985, 2021). "Further studies demonstrated that exosomes secreted by cervical cancer cells can deliver miR-663b to HUVECs and inhibit the expression of VCL, thereby promoting angiogenesis and tumor growth." (PMID 34923985, 2021). "The proteins with the highest betweenness were 14-3-3ζ, vimentin and vinculin, part of our central core of cervical cancer proteins, which is consistent with their role as bait proteins." (PMID 21696634, 2011). "Of the 17 downregulated proteins, 6 different proteins showed low expression in both vaginal and cervical carcinoma compared with normal vaginal tissue (calreticulin, tropomyosin 2 beta, vimentin, gelsolin, vinculin and filamin)." (PMID 19367286, 2009). "However, few studies have explored the biological role of VCL in cervical cancer metastasis and angiogenesis." (PMID 34923985, 2021). "Our research innovatively found that exosomes secreted by CaSki cells could carry miR-663b to HUVECs to promote cervical cancer angiogenesis by inhibiting the expression of VCL." (PMID 34923985, 2021). "We explored the expression of VCL in cervical cancer from clinical samples." (PMID 34923985, 2021). "Similarly, in this study, low levels of both vinculin and filamin were detected in vaginal and cervical carcinoma, indicating that these proteins are important for malignant transformation." (PMID 19367286, 2009). "In both vaginal and cervical carcinoma there was a downregulation of vimentin, filamin, tropomyosin 2 (TM2 beta) as well as vinculin." (PMID 19367286, 2009). "VCL is downregulated in cervical cancer, and decreased VCL has a negative correlation with a high level of miR-663b." (PMID 34923985, 2021). "Moreover, the level of miR-663b had a negative correlation with VCL protein, which was significantly downregulated in cervical cancer tissues." (PMID 34923985, 2021). "In addition, experiments on whether there is an interaction between VCL and the angiogenesis-targeted drug Bevacizumab were not carried out, also the signaling pathways involved in miR-663b/VCL axis in cervical cancer angiogenesis need further research." (PMID 34923985, 2021).
colorectal cancer (6 papers, 2014 to 2022). A primary or metastatic malignant neoplasm that affects the colon or rectum. "It has also been reported that the loss of VCL promotes metastasis and predicts poor prognosis in colorectal cancer." (PMID 34590603, 2021). "In addition, the loss of vinculin and membrane-bound β-catenin promotes metastasis in colorectal cancer and may also play a role in progression of other cancer types." (PMID 34277614, 2021). "The mechanoeffector protein vinculin is deregulated in gastrointestinal diseases, with expression levels reduced in colorectal cancers and auto anti-vinculin antibodies are produced in inflammatory bowel syndrome." (PMID 36269226, 2022). "In addition, the expression of VCL in highly metastatic colorectal cancer (CRC) cell lines and metastatic tissues was significantly downregulated and became an independent prognostic factor for CRC." (PMID 34923985, 2021).
colon carcinoma (5 papers, 2016 to 2023). "Through PIP2 mediated vinculin activation, PIPKIγ might positively regulate focal adhesion dynamics and colon cancer cell invasion." (PMID 30881993, 2019). "Vinculin, a cytoskeletal protein which links integrin adhesion molecules to actin, was reported as the main target of mAR activation that may regulate cell motility since inhibition of vinculin via phosphorylation promotes colonic cancer cell migration." (PMID 27833666, 2016). "Proteins of the actin cytoskeleton were more abundant in DM cells, one of which was vinculin, an actin filament-binding protein associated with cell differentiation status, locomotion, and PI3K/AKT, E-cadherin, and β-catenin-regulated WNT signaling in colon carcinoma." (PMID 32245408, 2020).
renal cell carcinoma (5 papers, 2009 to 2025). "Among the differential diagnoses that should be considered are: collecting duct carcinoma, malignant rhabdoid tumor, urothelial carcinoma, renal cell carcinoma with vinculin-ALK translocation-anaplastic lymphoma kinase (VCL-ALK), among others." (PMID 40777608, 2025). "As mentioned, the main differential diagnoses include collecting duct carcinoma (CDC), urothelial carcinoma, malignant rhabdoid tumor of the kidney, and renal cell carcinoma with VCL-ALK translocation." (PMID 40777608, 2025). "Some of the classical gene fusion examples involving a kinase-coding gene are EML4-ALK in lung adenocarcinoma, ALK-RET in colorectal cancers, and VCL-ALK in renal cell carcinoma (RCC)." (PMID 29455652, 2018). "Recently, echinoderm microtubule-associated protein-like 4 (EML4)-ALK fusion and vinculin (VCL)-ALK fusion have also been identified in non-small cell lung cancer (NSCLC) and renal cell carcinoma, respectively, which has not been described in IMT or EIMS yet." (PMID 26178751, 2015). "Vimentin and vinculin did not contribute much in differentiating subtypes of renal cell carcinomas." (PMID 19558708, 2009).
bladder cancer (4 papers, 2020 to 2025). "Previous studies have shown that Vinculin (VCL) expression is downregulated in bladder cancer with tumor suppressor gene properties, which is consistent with the results of the present study." (PMID 41181151, 2025). "further confirmed that VCL can be used as a potential protein marker for bladder cancer and provided strong support for the results of this study." (PMID 41181151, 2025). "VEGFA was most enriched in bladder cancer, and VCL was highly related to vascular smooth muscle contraction." (PMID 34112125, 2021). "VCL may be a key protein marker and pathway related to bladder cancer by mass spectrometry and bioinformatics analysis." (PMID 32547947, 2020). "The results of the analysis showed that seven genes (VCL, FLNA, THBS1, TAGLN, ACTA2, COL6A2, and CALD1) were significantly correlated (P < 0.05) with the prognosis of bladder cancer patients, and these genes were included in the subsequent in-depth study." (PMID 41181151, 2025). "Finally, six B-cell marker genes (VCL, FLNA, TAGLN, ACTA2, COL6A2, and CALD1) that were downregulated in bladder cancer were screened using the PPI network, survival curves, ROC curve analysis, and expression validation." (PMID 41181151, 2025). "Overall, Alterations in the expression of VCL, FLNA, TAGLN, ACTA2, COL6A2, and CALD1 may play important roles in the development of bladder cancer, suggesting their potential value in early detection, molecular subtyping, and targeted therapy." (PMID 41181151, 2025).
coronary artery disease (4 papers, 2022 to 2024). "Moreover, this condition stimulated increased actin stress fibers (phalloidin-TRITC labeling), focal adhesions (vinculin immunostaining), and cell-cell adhesion (junctional protein associated with coronary artery disease [JCAD] immunostaining) compared with control cells." (PMID 39641270, 2024).
gastric cancer (4 papers, 2021 to 2023). A primary or metastatic malignant neoplasm involving the stomach. "The role and mechanism of action of vinculin have been controversial, but this molecule may downregulate EpCAM (epithelial cellular adhesion molecule) and its own role in gastric cancer through DNA methylation, causing NK cells to enrich into tumor cells and kill tumor cells." (PMID 33535187, 2021). "Based on the data of TCGA and GEO patients, 1,253 patients with gastric cancer were included for statistical analysis and the high expression of VCL was found to be significantly correlated with the prognosis of patients." (PMID 33535187, 2021). "To verify the effect of vinculin on tumor cells, we had knocked down vinculin in gastric cancer cell lines in vitro to verify the effect of vinculin on tumors, and found that vinculin can play an important role by regulating the expression of EPCAM." (PMID 33535187, 2021). "By comparing the expression of VCL in gastric tissue samples from the TCGA gastric cancer database and the GTEx database, the expression of VCL in gastric cancer tissue was found to be significantly higher than that in normal gastric cancer tissue." (PMID 33535187, 2021). "From the QPCR data of the 56 patients available in the Gastric Cancer Center of Sun Yat-sen University, the expression of VCL was proven to be significantly related to the cancer’s aggressiveness (T staging) and distant metastasis capabilities." (PMID 33535187, 2021). "The influence of vinculin on the prognosis of gastric cancer has always been controversial." (PMID 33535187, 2021). "It proved that VCL may have important significance in the occurrence and development of gastric cancer." (PMID 33535187, 2021). "Therefore, through our large amount of clinical data and TCGA and other database mining, we first confirmed that vinculin had an important influence on the migration and metastasis of gastric cancer." (PMID 33535187, 2021). "Vinculin has an important relationship with the prognosis and metastasis of gastric cancer patients, and for that, whether we can find its target and allow for precision therapy, is another question that we will have to answer in the future." (PMID 33535187, 2021). "Moreover, the expression of VCL was significantly correlated with distant metastasis of gastric cancer." (PMID 33535187, 2021). "It showed that VCL had an important influence on the invasion and metastasis of gastric cancer." (PMID 33535187, 2021). "By analyzing the DNA methylation data of TCGA gastric cancer database, there were 12 DNA methylation sites in VIM, 8 in CDH1, 3 in S100A4, 7 in EPCAM, and 6 in VCL." (PMID 33535187, 2021). "The immunohistochemical status of 56 patients was analyzed and found that VCL expression was positively correlated with VIM and negatively correlated with ECAD, indicating that VCL had an important relationship with the development of EMT in gastric cancer." (PMID 33535187, 2021).
myocardial infarction (4 papers, 2022 to 2025). Gross necrosis of the myocardium, as a result of interruption of the blood supply to the area, as in coronary thrombosis. "This research highlights key genes associated with mitochondrial oxidative stress—VCL, ABCB1, JAK2, KDR, NGF—that show differential expression in DCM and myocardial infarction." (PMID 40217309, 2025). "To investigate whether VCL pY822 expression changes in response to injury, we used a myocardial infarction (MI) model to induce ischemic injury in the adult heart." (PMID 41231303, 2025).
ventricular tachycardia (4 papers, 2010 to 2021). A disorder characterized by an electrocardiographic finding of three or more consecutive complexes of ventricular origin with a rate greater than a certain threshold (100 or 120 beats per minute are commonly used). "Cardiac-specific ablation of vinculin exhibits pathological abnormalities and may lead to ventricular tachycardia." (PMID 33670798, 2021). "Moreover, that the knockout of vinculin, a protein that connects myocardial cells and extracellular matrix, reduces Cx43 expression and increases the incidence of ventricular tachycardia." (PMID 25237357, 2014).
viral infection (4 papers, 2020 to 2023). "Moreover, VCL has been associated with immune function, reducing the susceptibility to virus infections." (PMID 36670844, 2023). "This study demonstrated that the synergistic effect between DENV2 infection and TNF-α induction could demolish moesin expression, redistribute vinculin, and reorganize the actin cytoskeleton during virus infection." (PMID 34696472, 2021). "In conclusion, using proteomic analysis we found that the DEPs SPP1, IFIT5, ISG15, VCL, and SDC1 are significantly changed in PSV-infected PK-15 cells, suggesting that these proteins may be closely related to viral infection." (PMID 32575635, 2020).
cerebral malaria (3 papers, 2009 to 2018). A sequestration of Plasmodium falciparum in the brain, which can cause coma and/or seizures. "In the setting of infection such as cerebral malaria, ZO-1, occludin, and vinculin are downregulated." (PMID 30259344, 2018). "Destruction of EC-junction proteins--ZO-1, occludin and vinculin--in cerebral malaria has been reported." (PMID 24884882, 2014). "Those cultured with samples from severe malaria had no change in mRNA levels, and HUVECs cultured with P. falciparum from patients with cerebral malaria had decreased mRNA levels of occludin, vinculin, and ZO-1." (PMID 19680452, 2009).
Chlamydia infection (3 papers, 2015 to 2019). "In Chlamydia infection, vinculin has been implicated in RNA interference screens, but the molecular basis for vinculin requirement has not been characterized." (PMID 26649283, 2015). "It has previously been shown that the interaction between TarP and vinculin is required for Chlamydia infection." (PMID 29710402, 2018). "The precise role of vinculin during Chlamydia infection and whether it cooperates with the ABDs and FABs of the TarP family during invasion remains unknown at present." (PMID 30629647, 2019). "Interestingly, the recruitment of vinculin observed during Chlamydia infection was due to a C-terminal VBD within TarP." (PMID 26649283, 2015).
endometriosis (3 papers, 2018 to 2025). The growth of functional endometrial tissue in anatomic sites outside the uterine body. "They identified CLIC4, RTN4, and VCL as the target genes, and proposed that upregulation of miR-199a in endometriosis regulates adhesion and infiltration of endometrial cells by targeting these genes." (PMID 29463003, 2018). "Furthermore, based on immunofluorescence, the increase in actin and vinculin expression was detected in normal ESC in comparison to cells affected by endometriosis." (PMID 33499261, 2021). "However, they collectively indicate that VCL may play a significant role in the development of endometriosis, with external factors such as inflammation and the expression of microRNAs influencing VCL expression in endometrial cells." (PMID 40072086, 2025).
glioblastoma (3 papers, 2015 to 2020). The most malignant astrocytic tumor (WHO grade IV). "We analyzed the focal adhesion structures in glioblastoma cells using immunostaining for an integrin-associated linker protein, vinculin." (PMID 33008000, 2020). "Our functional enrichment of genes in patient tumors revealed that low expression of RND1 in glioblastoma induces an overexpression of focal adhesion proteins like extracellular matrix proteins (COL1A1 and LAMB1); integrins (ITGA5 and ITGB1); actin-binding proteins (FLNA; ACTN1) and vinculin." (PMID 30333910, 2018).